HTR3D (5-hydroxytryptamine receptor 3D)
Description:
Forms serotonin (5-hydroxytryptamine/5-HT3)-activated cation-selective channel complexes, which when activated cause fast, depolarizing responses in neurons.
Synonyms: 5HT3D
Tractability: Small molecule: an approved drug acts on it; a high-quality ligand is known; it belongs to a druggable protein family. Antibody: UniProt places it where antibodies can reach, with high confidence; its Gene Ontology location is reachable by antibodies, with high confidence; UniProt predicts a signal peptide or a membrane-spanning region. PROTAC: a small molecule that binds it is known.
Gene: Protein-coding gene on chromosome 3 (184,031,544 to 184,039,369, forward strand). Ensembl gene ENSG00000186090.
Subcellular location: Postsynaptic cell membrane; Cell membrane
Pathways (Reactome):
Neuronal System: Neurotransmitter receptors and postsynaptic signal transmission
Gene Ontology:
Molecular function: protein binding; serotonin-gated monoatomic cation channel activity; extracellular ligand-gated monoatomic ion channel activity; monoatomic ion channel activity; transmembrane signaling receptor activity
Biological process: serotonin receptor signaling pathway; serotonin-gated cation-selective signaling pathway; transmembrane transport; calcium ion transport; monoatomic ion transmembrane transport; monoatomic ion transport
Cellular component: plasma membrane; serotonin-activated cation-selective channel complex; neuron projection; synapse; transmembrane transporter complex; membrane; postsynaptic membrane
Genetic constraint (gnomAD): Loss-of-function variants: 45 observed, 45.02 expected, observed/expected ratio (o/e) 1, 90% interval 0.79 to 1.28. The upper end of that interval is the gene's LOEUF score, 1.28, which puts it in group 5 of 6, group 1 being the genes least tolerant of losing a copy. Missense variants: 431 observed, 502.83 expected, observed/expected ratio (o/e) 0.86, 90% interval 0.79 to 0.93. Synonymous variants: 190 observed, 195.6 expected, observed/expected ratio (o/e) 0.97, 90% interval 0.86 to 1.1.
Homologues: Orthologues: macaque HTR3D (75% identical). Paralogues in human: HTR3E (61% identical), HTR3C (54% identical), HTR3A (27% identical), HTR3B (19% identical), CHRNA7 (18% identical), CHRNA10 (17% identical), CHRNB3 (17% identical), CHRNA1 (17% identical), CHRNA4 (16% identical), CHRNB1 (16% identical), CHRNB2 (16% identical), CHRND (16% identical), and 33 more.
Diseases named in the same sentence as HTR3D in open-access papers:
HTR3D is named in the same sentence as 3 diseases in open-access papers, as found by Europe PMC text mining. Sharing a sentence is not in itself a finding about the gene and the disease. The quoted sentences say what the papers report.
lung carcinoma (1 paper, 2021). "In this study, HTR3 family members were assessed in NSCLC patients, which showed that HTR3C, HTR3D, and HTR3E were amplified with high frequency among lung cancer patients." (PMID 34868311, 2021).
Stroke (1 paper, 2025). Sudden impairment of blood flow to a part of the brain due to occlusion or rupture of an artery to the brain. "HTR3D and NEUROG3 were linked with the susceptibility of PSD and PIK3C2B with stroke in the Chinese Han population." (PMID 40529498, 2025).
HTR3D also shares sentences with these, for which no sentence is quoted: tumor (1 paper).